NSMCE2 (NSE2 SUMO ligase component of SMC5/6 complex)
Diseases named in the same sentence as NSMCE2 in open-access papers:
NSMCE2 is named in the same sentence as 27 diseases in open-access papers, as found by Europe PMC text mining. Sharing a sentence is not in itself a finding about the gene and the disease. The quoted sentences say what the papers report.
Seckel syndrome (6 papers, 2018 to 2023). A rare autosomal recessive inherited syndrome caused by mutations in the ATR gene, RBBP8 gene, CENPJ gene, CEP152 gene, CEP63 gene, NIN gene, DNA2 gene, or TRAIP gene. "Seckel syndrome is genetically heterogeneous, and mutations in DDR genes (ATRIP and ATR), DNA repair factors (NSMCE2, DNA2, TRAIP and CtIP) and components of the centrosome (NIN, CEP63, CEP152 and CENPJ) have been reported." (PMID 32994318, 2020). "Other forms of Seckel syndrome are caused by mutations in genes associated with cell growth (TRAIP), genomic integrity and repair (ATR, NSMCE2, DNA2, and RBBP8), centrosome function (NIN, CEP63)." (PMID 29504900, 2018). "Like mitochondrial myopathy, Seckel syndrome is genetically heterogeneous and disease mutations affect groups of genes with roles in DNA replication/repair (ATR, DNA2, CTIP, NSMCE2, and TRAIP) and segregation of the replicated genome into daughter cells (CEP63, CEP152, CENPJ, NIN, and NSMCE2)." (PMID 33924313, 2021).
breast carcinoma (5 papers, 2016 to 2022). "An overall survival analysis showed that a high expression of NSMCE2 was associated with a worse outcome in breast cancer patients." (PMID 33214551, 2020). "We bioinformatically identified two novel super-enhancer-associated genes – NSMCE2 and MAL2 – highly upregulated in breast tumors, for which high RNA levels significantly and specifically correlate with breast cancer patients’ poor prognosis." (PMID 36224576, 2022). "Taken together, these results show that reducing NSMCE2 levels sensitizes breast cancer cells to chemotherapy, thus implying that NSMCE2 high levels contribute resistance to chemotherapeutic agents." (PMID 36224576, 2022). "Through pharmacological SE disruption assays performed in breast cancer cell lines, we experimentally confirmed that SEs regulate the expression of NSMCE2 or MAL2." (PMID 36224576, 2022). "In summary, pharmacological blockade of SEs confirmed NSMCE2 and MAL2 are associated with SEs in breast cancer cells." (PMID 36224576, 2022). "Treatment of breast cancer cells with SE inhibitor JQ1 abrogates the effect of doxorubicin in NSMCE2 upregulation, indicating that NSMCE2 upregulation by doxorubicin is mediated by SEs." (PMID 36224576, 2022). "High gene expression levels of NSMCE2 correlate with breast cancer patients’ poor response to chemotherapy." (PMID 36224576, 2022). "Using ROC Plotter, we found that high levels of NSMCE2 gene expression correlate with lower pathological complete response to chemotherapy of breast cancer patients (Mann–Whitney test p-value = 0.000032 and AUC = 0.617)." (PMID 36224576, 2022). "In line with what we observed in breast cancer, NSMCE2 or MAL2 are significantly higher in the cancer samples compared to the normal corresponding samples in most of the cancer types studied." (PMID 36224576, 2022). "Moreover, we found that high levels of NSMCE2 gene expression strongly correlate with poor response to chemotherapy for patients diagnosed with grade III breast cancer (Mann–Whitney test p-value = 0.00099 and AUC = 0.655)." (PMID 36224576, 2022). "On the METABRIC dataset, high expression of MAL2 significantly associates with worse overall survival of breast cancer patients, while high NSMCE2 follows the same trend without reaching statistical significance." (PMID 36224576, 2022). "Next, we investigated in other cancer types (apart from breast cancer) whether expression of NSMCE2 and MAL2 is higher in tumor samples when compared to normal tissue and whether high levels of any of these two genes associate with poor survival." (PMID 36224576, 2022). "In line with this, we found that NSMCE2 RNA expression increases upon doxorubicin treatment in breast cancer cells, suggesting that NSMCE2 upregulation could be required to overcome doxorubicin induced DNA damage." (PMID 36224576, 2022). "Also in cancer, NSMCE2 depletion has been reported to prevent cell cycle progression of breast cancer cells." (PMID 36224576, 2022). "Finally, we showed that decreasing NSMCE2 gene expression increases breast cancer cells’ sensitivity to chemotherapy treatment." (PMID 36224576, 2022). "Lowering NSMCE2 transcript levels sensitizes breast cancer cells to chemotherapeutic agents." (PMID 36224576, 2022). "Thus, our results indicate that breast cancer patients with high NSMCE2 RNA expression in aggressive breast tumors of either TN or HER2 + molecular subtype respond poorly to chemotherapeutic drugs." (PMID 36224576, 2022). "In summary, our results demonstrate that JQ1 synergizes with doxorubicin to induce apoptosis suggesting that reducing NSMCE2 expression by SE inhibition may contribute to the increase in apoptosis of the breast cancer cell lines tested." (PMID 36224576, 2022). "NSMCE2 was required for G1-S transition in breast cancer cells and manipulation of NSMCE2-mediated sumoylation may alter the growth rates of breast cancer cells." (PMID 28415592, 2017).
breast carcinoma (continued). "Thus, although NSMCE2 and MAL2 are highly expressed in Pan-Cancer tumors, their association to patients’ negative survival outcomes is specific to certain cancer types, including breast cancer." (PMID 36224576, 2022). "Collectively, our results show that NSMCE2 expression is transcriptionally upregulated upon doxorubicin treatment through SEs, and this could be a factor contributing to resistance to chemotherapy during breast cancer treatment." (PMID 36224576, 2022). "Given that our data shows that high NSMCE2 and MAL2 expression are associated with breast cancer patients’ poor survival outcomes, we next investigated if high levels of these markers could also be negatively associated with response to standard cancer therapies." (PMID 36224576, 2022). "Since we found that SEs are associated to NSMCE2 and MAL2 expression in breast tumors, we hypothesized that in breast cancer cells, expression of these genes should be reduced when disrupting the SE-enhancing function by blocking the binding of BRD4 to SEs with the inhibitors JQ1 or IBET151." (PMID 36224576, 2022). "Importantly, by generating NSMCE2 knockdown breast cancer cell lines, we showed that NSMCE2 plays a key role in resistance to doxorubicin treatment, probably due to its DNA repairing function, which reduces doxorubicin’s DNA damaging effect and prevents the activation of the apoptotic program." (PMID 36224576, 2022). "Moreover, through analyses of tumor microarray data linked to therapy response of cancer patients, we found that high expression of NSMCE2 predicts poor response to chemotherapeutic drugs for patients diagnosed with breast cancer, especially patients diagnosed with aggressive TN or HER2 + tumors." (PMID 36224576, 2022). "To test whether reduction of NSMCE2 transcript levels by SE disruption can sensitize breast cancer cells to chemotherapy-induced apoptosis, we treated breast cancer cells with BET inhibitor JQ1 and the standard chemotherapeutical drugs doxorubicin and paclitaxel." (PMID 36224576, 2022). "Through mining genomic datasets, we also found that NSMCE2 and MAL2 are frequently amplified in breast cancer patients and in breast cancer cell lines." (PMID 36224576, 2022). "These known tumor-promoting roles for NSMCE2 and MAL2 suggest that SE-driven overexpression of these two genes can support a variety of tumor-promoting processes in breast cancers cells." (PMID 36224576, 2022). "We found that high transcript levels of 3 genes – NSMCE2, MAL2 and EIF3H – significantly correlate with worse overall survival in breast cancer patients (Log-rank test, p-value < 0.05)." (PMID 36224576, 2022). "Thus, frequent copy number gains of the NSMCE2 and MAL2 loci in breast cancer suggest that higher gene expression levels for these genes indeed contribute to tumor progression." (PMID 36224576, 2022). "Importantly, by mining a database containing breast cancer treatment and response information, we found that high levels of NSMCE2, especially in grade III TN and HER2 + breast cancers, are strongly correlated with patients’ poor response to chemotherapy." (PMID 36224576, 2022). "Importantly, our computational analyses show that high NSMCE2 gene expression levels correlate to patients’ poor response to chemotherapy, especially in grade III TN and HER2 + breast cancers." (PMID 36224576, 2022). "Similarly, NSMCE2 plays an important role in cell cycle, since its depletion in MCF-7 breast cancer cells affected cell cycle and G1-S transition." (PMID 29938003, 2018). "Our results suggest that inhibiting NSMCE2 function by pharmacological inhibition or gene expression reduction (e.g., through SE blockade), could sensitize breast cancer cells to chemotherapy in specific cohorts of breast cancer patients that do not respond to standard antitumor drugs." (PMID 36224576, 2022).
breast carcinoma (continued). "By using this approach, we identified two highly upregulated genes in tumors, NSMCE2 and MAL2, for which high levels of gene expression significantly correlate with breast cancer patients’ negative prognosis." (PMID 36224576, 2022).
Insulin resistance (4 papers, 2017 to 2024). Increased resistance towards insulin, that is, diminished effectiveness of insulin in reducing blood glucose levels. "For example, SMC5/6-destabilizing mutations in NSMCE3 cause lung disease-immunodeficiency-chromosomal breakage syndrome (LICS), and NSMCE2 or SMC5 mutations result in primordial dwarfism and insulin resistance." (PMID 38886582, 2024).
leukemia (2 papers, 2024 to 2025). A malignant (clonal) hematologic disorder, involving hematopoietic stem cells and characterized by the presence of primitive or atypical myeloid or lymphoid cells in the bone marrow and the blood. "PVT1-NSMCE2: In leukemia cells with double minute chromosomes, which are small fragments of extrachromosomal DNA present in many human tumors, three fusion transcripts of PVT1 and the protein-coding gene NSMCE2 were identified in AML patients and cell lines of similar origin." (PMID 38919532, 2024).
microcephaly (2 papers, 2020 to 2023). A congenital or acquired developmental disorder in which the circumference of the head is smaller than normal for the person's age and sex. "Mutation of NSMCE2 causes primordial dwarfism and primary congenital microcephaly in humans and promotes cancer development and premature aging in mice." (PMID 33200984, 2020). "Moreover, mutation of NSMCE2 causes primordial dwarfism and primary congenital microcephaly." (PMID 33200984, 2020). "The first identified patient with cardiac disease carried a variant in NSMCE2, a component of the SMC5/6 complex, which causes primordial dwarfism with microcephaly." (PMID 38203602, 2023).
osteosarcoma (2 papers, 2016 to 2022). A usually aggressive malignant bone-forming mesenchymal neoplasm, predominantly affecting adolescents and young adults. "By using a human osteosarcoma cell line (U2OS), we show that after the CRISPR-Cas9-mediated removal of the SMC5/6 subunit NSMCE2, treatment with the topoisomerase II inhibitor etoposide triggered an increased sensitivity in cells lacking NSMCE2." (PMID 27792189, 2016).
acanthosis nigricans (1 paper, 2019). A melanotic cutaneous lesion that develops in the axilla and other body folds. "Hypomorphic NSMCE2 mutation in humans is associated with a syndrome characterized by short stature and acanthosis nigricans." (PMID 30735491, 2019).
Atelís Syndrome (1 paper, 2022). "Taken together, we have demonstrated that variants in two components of the RAD18-SLF1/2-SMC5/6 pathway give rise to a FA/MVA-like disorder, termed Atelís Syndrome, with clinical and cellular features overlapping with WABS, MVA, NSMCE2 variants and FA." (PMID 36333305, 2022).
breast tumors (1 paper, 2022). "Altogether, our experimental findings imply that combining SE blockade with doxorubicin can be an effective therapy to treat breast tumors that express high levels of NSMCE2." (PMID 36224576, 2022). "In conclusion, our work demonstrates for the first time that in breast tumors NSMCE2 and MAL2 can be dysregulated by SEs, are frequently amplified, and thus, overexpressed." (PMID 36224576, 2022). "In sum, our experiments show that the correlation between high NSMCE2 expression levels in breast tumors and cancer patients’ poor response to chemotherapy is due, in part, to increased resistance to chemotherapeutic drugs driven by NSMCE2." (PMID 36224576, 2022). "Although we ignore the epigenetic modifications as well as the gene expression changes occurring in response to treatment in these breast tumors, this correlation also points to the role of NSMCE2 on resistance to chemotherapy." (PMID 36224576, 2022).
Majewski syndrome (1 paper, 2025). "Endocrine dysfunction, well reported in XRCC4-related MPD, is also observed in other DNA repair defects, including DNA2, BLM, NSMCE2-related MPD [MIM#615807, MIM#210900, MIM#617253], but also in other MPD such as Majewski syndrome." (PMID 40114033, 2025).
cancer (9 papers, 2016 to 2024). A tumor composed of atypical neoplastic, often pleomorphic cells that invade other tissues. "One study found that conditional knockout (cKO) of Nsmce2 in mice during adulthood causes premature aging and susceptibility to cancer." (PMID 33200984, 2020). "Moreover, loss of Smc5/6 may predispose cells to genetic errors under conditions of DNA damage (e.g., induced by necroinflammation in CHB), and reduced expression of the NSMCE2 (Nse2) subunit is associated with increased cancer incidence in mice." (PMID 28368357, 2017). "NSMCE2 is an SMC5-SMC6 complex SUMO ligase that has been studied in mice in the context of cancer suppression and aging." (PMID 35565187, 2022). "Previously it was reported that NSMCE2 is involved in maintaining telomeres’ length in cancer cell lines, in this manner preventing telomere-mediated cell cycle arrest and the activation of the senescence pathway." (PMID 36224576, 2022). "The identification of NSMCE2 as a potential controller of HR-mediated fork rescue highlights NSMCE2’s potential as a new therapeutic target for combinatorial therapy of HR-dependent cancers." (PMID 30735491, 2019). "NSMCE2 has also been shown to be essential for mouse development and it can suppress cancer and aging by limiting recombination and facilitating chromosome segregation." (PMID 27792189, 2016). "So, we further analyzed the methylation levels of these genes in pan-cancer, and we found that most of them, such as SPP1, RHBDF1, and NSMCE2, were significantly demethylated, which was consistent with the high expression of these genes specifically in tumors." (PMID 37723560, 2023). "This decreased growth rate was rescued by ectopic expression of Flag-NSMCE2 but not its SUMO ligase-inactive mutant, suggesting that the SUMO ligase activity of NSMCE2 ensures proper G1-S transition in these human cancer cells." (PMID 27792189, 2016).
tumor (3 papers, 2014 to 2022). "Since our results demonstrate that NSMCE2 and MAL2 gene expression levels are reduced by pharmacological SE blockade, targeting SEs could work as a therapeutic approach to reduce these tumor promoting processes." (PMID 36224576, 2022). "Since we also demonstrated that downregulation of NSMCE2 and MAL2 gene expression can be achieved by blocking SEs, collectively these data suggest that both mechanisms (i.e., SE-driven dysregulation and gene amplification) can increase expression of these oncogenes in tumor cells." (PMID 36224576, 2022).
cardiac disease (1 paper, 2023). "Recent work on NSMCE2 and SMC5 demonstrates that the p.Arg372del variant in SMC5 can destabilize the interaction of SMC5 and NSCME2, indicating that SMC5 variants can potentially play a role in heart disease by disrupting its interaction with NSMCE2." (PMID 38203602, 2023).
NSMCE2 also shares sentences with these, for which no sentence is quoted: lung adenocarcinoma (2 papers); lung disease (2); primordial dwarfism (2); colorectal cancer (1); diabetes (1); glioblastoma (1); insulin-resistant diabetes (1); lipodystrophy (1); Mitochondrial myopathy (1); Oral ulcer (1); ovarian carcinoma (1); pancreatic ductal adenocarcinoma (1); sarcoma (1); uveal melanoma (1).